PAX5 (paired box 5)
Diseases named in the same sentence as PAX5 in open-access papers (continued):
Sharing a sentence is not in itself a finding about the gene and the disease.
infection (continued). "First, we decreased the expression of Myd88 by generating Pax5+/−;Myd88+/− mice by interbreeding, and examined whether Pax5+/−;Myd88+/− animals were more prone to infection-induced B-ALL than Pax5+/− mice." (PMID 37620322, 2023). "Pax5+/−;Myd88+/− mice were exposed to natural infections, and B-ALL development was monitored." (PMID 37620322, 2023). "Furthermore, among the B220-positive B cells in the necrotic lesions, Pax5-positive immature B cells were identified as targets of SFTSV infection." (PMID 28194148, 2017). "Conditional Pdcd1fl/fl;Mb1-Cre;Pax5+/− mice were generated, where Pdcd1 is deleted upon B-lineage commitment at the pro-B-cell stage, and we examined whether Pdcd1fl/fl;Mb1-Cre;Pax5+/− animals were prone to infection-induced B-ALL." (PMID 41283237, 2025). "Thus, we first investigated if high levels of AID were present in in vivo preleukemic precursor B cells purified from mice carrying a genetic susceptibility to B-ALL (either Pax5 heterozygosity or the presence of the ETV6-RUNX1 fusion gene), which are exposed to natural infections." (PMID 31804490, 2019). "The number of mRNA copies of the B-cell-related genes Pax5, CD5, and CD19; T-cell-related gene CD8A; and MHC-related genes CIITA, HLA-DQ1, HLA-DR, and HLA-DO were significantly decreased in patients with infections." (PMID 40185975, 2025). "Two mouse models has been used to prove the interaction between infection and B-ALL development, the Pax5+/- and the Sca1-ETV6-RUNX1 mice that replicate the initial phase responsible for the predisposition to B-ALL observed in certain human patients." (PMID 37901253, 2023). "In addition, we found that Pax5, a master regulator of B cell development whose expression is maintained in memory B cells but lost in plasma cells, was upregulated in young naïve B cells at day 3 and day 9 post-infection and in young plasma cells at day 3 post-infection." (PMID 37852965, 2023). "Following infection in Kashmir favorella, three differentially expressed genes Nuclear Factor Kappa B (NF-κB1), Forkhead Box Protein O3 (FOXO3) and Paired box 5 (Pax5) were identified." (PMID 37098463, 2023). "To functionally demonstrate the role of IL-6, we impaired the expression of IL-6 by breeding Pax5+/- mice to IL-6+/− mice, which have significantly lower IL-6 serum concentrations, with the aim of testing whether IL-6+/-/Pax5+/- mice are more resistant to infection-induced B-ALL than Pax5+/- mice." (PMID 33154497, 2020). "Of these factors, Pax5 and Spib are predominantly expressed in B cells and silenced in T cells, yet their transient induction in WT CD8+ T cells during infection may indicate a previously unanticipated role for them in T cell function." (PMID 35944008, 2022). "Here we show that, surprisingly, AID genetic deletion does not affect B-ALL development in Pax5-haploinsufficient mice prone to B-ALL upon natural infection exposure." (PMID 31804490, 2019). "Likewise, immune training by early exposure to infection does not prevent Pax5+/− preleukemic carriers against B-ALL." (PMID 37620322, 2023). "On the contrary, the loss of Pax5 is critical for ETV6/RUNX1+ B-ALL developed, as the onset of the disease in Sca1-ETV6-RUNX1 + Pax5-het mice (62.5%) is drastically increased even in the absence of exposure to infections, compared to Sca1-ETV6-RUNX1 mice (10.75%) and exposed to infections." (PMID 34336858, 2021). "Thus, the combination of the first hit “Sca1-ETV6-RUNX1” and the second hit “Pax5-het” is what leads to B-ALL development without the need of exposure to infections as the second hit is already present." (PMID 34336858, 2021). "There were no apparent differences in PAX5-positive cells in NALT after primary infection." (PMID 30038294, 2018).
infection (continued). "Transcription levels of the myeloid-associated genes C/EBPα, PU.1, FOG1, and G-CSF were increased in total BM cells by 2–3-fold at 12 h post infection, while transcription levels of the lymphoid-associated genes IL7-R, Flt3, Rag1, PAX5, and Ikaros did not change at this time point." (PMID 23189271, 2012). "We infected Pax5-/+ mice with the noncytopathic Lymphocytic Choriomeningitis Virus (LCMV) and found that infection with the chronic Docile strain resulted in decreased survival of Pax5-/+ mice." (PMID 40082582, 2025). "However, the exposure to natural infection does not significantly increase AID expression in preleukemic precursor B cells, although in vitro exposure of preleukemic Pax5-het, and Sca1-ETV6-RUNX1 precursor pro-B cells to different immune activation stimuli resulted in high levels of AID mRNA." (PMID 31804490, 2019).
hematologic malignancies (8 papers, 2013 to 2025). "Interestingly, the lengths from amplified Pax-5 3′UTRs demonstrated a trend with hematopoietic disease malignancy." (PMID 35011638, 2021). "PAX5 (paired box 5), also known as BSAP (B-cell-specific activator protein), is the only PAX molecule that plays a role in the management of hematopoietic diseases." (PMID 40506992, 2025). "Compared with the patients with other hematological diseases, the patient had higher levels of LYL1, NOTCH1, PAX5, MYC, and E2B, all of which contribute to the development of T and B cells." (PMID 33126303, 2020).
adenocarcinoma (5 papers, 2016 to 2024). A common cancer characterized by the presence of malignant glandular cells. "Our results indicate that in NE-like cells, the Pax5 promoter is heavily methylated compared to adenocarcinoma cells and therefore raised the question of how a methylated Pax5 promoter becomes accessible for Pbx1 binding." (PMID 38168280, 2023). "Interestingly, our results showed that the 5hmC footprint at the upstream Pbx1 binding site of Pax5 promoter is higher in NE-like cells than in adenocarcinoma." (PMID 38168280, 2023). "Interestingly, while studying the Pax5 promoter regions, we found enhanced histone acetylation nearby the Pax5 promoter region of NE-like cells (C4-2BER) as compared to the adenocarcinoma cell line." (PMID 38168280, 2023). "Our results show that Pax5 is preferentially expressed in DKD, C4-2BER and NCI-H660 as compared to adenocarcinoma counterpart C4-2 and C4-2B respectively." (PMID 39183332, 2024). "Our results show that Pax5 is preferentially expressed in DKD and C4-2BER as compared to adenocarcinoma counterpart C4-2 and C4-2B respectively." (PMID 38168280, 2023). "While analyzing these CRPC-adenocarcinoma and t-NEPC patients’ individual expression for Pax5, ETV5 and KLF12, we further found that both ETV5 and KLF12 expression vary among adenocarcinoma and t-NEPC patients, with sometimes showing higher expression in CRPC adenocarcinoma." (PMID 39183332, 2024). "To understand whether Pax5 expression is specific to t-NEPC, we have analyzed both RNA and protein expression of Pax5 in our models and compare them with CRPC adenocarcinoma cell lines." (PMID 39183332, 2024). "Again, Pax5 expression is not detected in metastatic CRPC (mCRPC) cases diagnosed with adenocarcinoma, but were present in those with t-NEPC, which supports that Pax5 expression is specific to the NE-like lineage differentiation of PCa." (PMID 38168280, 2023). "To determine whether demethylation of CpG region favors chromatin accessibility at the Pax5 promoter, we analyzed the promoter methylation status of adeno and NE-like cells by performing EPIC Methylation Array between adenocarcinoma (C4-2) and NE-like cells (DKD)." (PMID 38168280, 2023). "The absence of Pax5 in any of the adenocarcinoma tissue indicates that Pax5 expression might be specific transcriptional event in NE-subtype." (PMID 38168280, 2023). "Interestingly, ectopic expression of Pax5 alone in adenocarcinoma cells did not transduce these cells into NE-like phenotype." (PMID 38168280, 2023). "Although PBX1 expression increases significantly from adenocarcinoma towards t-NEPC transformation, we questioned to understand what favors differential recruitment of PBX1 in Pax5 promoter in NE-like cells but not in adenocarcinoma." (PMID 38168280, 2023).
neurodevelopmental disorder (4 papers, 2017 to 2025). A behavioral and cognitive disorder with onset during the developmental period that involves impaired or aberrant development of intellectual, motor, or social functions. "Notably, Pax5+/− mice exhibited abnormal social and repetitive behaviors, coordination deficits, hyperactivity, and sensorimotor performance and learning deficits, albeit often in a milder form, indicating that PAX5 haploinsufficiency is already sufficient to cause a neurodevelopmental disorder." (PMID 35947077, 2022). "Moreover, genomic deletions of 5’-exons have been described in patients with neurodevelopmental disorders, and an aberrant gene fusion of 5’-PAX5 and 3’-AUTS2 in B-ALL patients results in losses of anterior parts of AUTS2 protein." (PMID 28977998, 2017).
Hematopoietic Cancers (3 papers, 2021 to 2025). "PAX5, in turn, plays an important role in B-cell lineage commitment and maturation, and represents a potent oncogene in hematological cancers." (PMID 41009355, 2025). "Accordingly, the methylation profile of the PAX5 promoter region has been proposed as a potential tool with clinical applicability for prognostics and diagnostics in the classification of non-hematological cancer subtypes." (PMID 36077495, 2022). "In contrast to B-cells, the functional role and outcome of aberrant PAX5 expression in non-hematological cancers are as diverse as the types of tissue that express PAX5." (PMID 36077495, 2022). "Given its pivotal regulatory function in B-cell development, Pax-5 is also involved with the onset and progression of various hematological cancers and some carcinomas." (PMID 35011638, 2021). "More importantly, we found that advanced staging of various hematopoietic cancer lesions relates to shorter Pax-5 3′UTRs." (PMID 35011638, 2021). "PAX5 mRNA shortening was also investigated in non-hematological cancers." (PMID 36077495, 2022). "On the other hand, PAX5 could also represent a potent therapeutic target for many hematological cancer lesions." (PMID 36077495, 2022).
blood cancer (2 papers, 2022 to 2024). "This review mainly focuses on the effects of EBF1, PAX5, and MYC on B cell development and their association with hematologic neoplasms." (PMID 38318177, 2024). "In short, as pivotal TFs in B cell development, the abnormalities of EBF1, PAX5, and MYC result in hematologic tumors." (PMID 38318177, 2024). "To test whether enforced FOXO1 expression is sufficient to induce EBF1, IRF4, or PAX5 expression in non-B-lineage blood cancer cells, we next transduced lentivirus encoding FOXO1 into the AML cell lines HEL and THP1, which express negligible levels of EBF1, FOXO1, IRF4, and PAX5." (PMID 36282572, 2022). "Given that the aberrant expression and function of EBF1, PAX5, and MYC contribute to hematologic neoplasms, therapies targeting them may shed light on these diseases." (PMID 38318177, 2024).
bacterial infections (1 paper, 2023). "The differentially expressed genes NF-κB1, FOXO3 and PAX5 are involved in defending the host against bacterial infections were significantly enriched in the indigenous breed Kashmir favorella." (PMID 37098463, 2023).
PAX5 also shares sentences with these, for which no sentence is quoted: multiple myeloma (8 papers); follicular lymphoma (7); acute myeloid leukemia (6); lymphoid leukemia (4); neuroendocrine tumors (3); breast tumor (2); immune disease (2); Kidney Disease (2); myelodysplastic syndrome (2); schizophrenia (2); squamous carcinoma (2); acute kidney injury (1); adrenocortical cancers (1); adult T-cell leukemia (1); anaplastic thyroid carcinoma (1); asthma (1); autoimmune disease (1); B cell deficiency (1); B cell lymphopenia (1); bipolar disorder (1); bone marrow failure (1); brain tumours (1); Castleman disease (1); cerebral amyloid angiopathy (1); chordoma (1); chronic hepatitis (1); CNS germ cell tumors (1); CNS lymphoma (1); Cognitive impairment (1); cutaneous T-cell lymphoma (1).
A further 54 diseases each share a sentence with PAX5 in 1 paper.